PPP1R12A (protein phosphatase 1 regulatory subunit 12A)
Diseases named in the same sentence as PPP1R12A in open-access papers:
PPP1R12A is named in the same sentence as 79 diseases in open-access papers, as found by Europe PMC text mining. Sharing a sentence is not in itself a finding about the gene and the disease. The quoted sentences say what the papers report.
colon cancer (7 papers, 2015 to 2024). "For instance, PPP1R12a-73aa, encoded by circPPP1R12a, promotes the proliferation and metastasis in colon cancer." (PMID 36064939, 2022). "Also, low RCN of PPP1R12A was associated with poor RFS in colon cancer with significance (P = 0.037)." (PMID 26113782, 2015). "For example, circPPP1R12A, which is produced by exons 24/25 of PPP1R12A, encodes a 73 amino-acid small peptide (named “PPP1R12A-73aa peptide”); it is circPPP1R12A-73aa rather than circPPP1R12A that has a tumor-suppressor role in colon cancer because it activates the Hippo-YAP signaling pathway." (PMID 34055634, 2021). "For example, circRNA PPP1R12A promoted the activation of Hippo/YAP signaling to drive metastasis of colon cancer." (PMID 39166861, 2024). "In contrast to PPP1R12A, PPP1R12A-73aa exerts pro-carcinogenic activity, and the expression profiles of circRNAs in colon cancer cells revealed an increased level of circPPP1R12A (hsa_circ_0000423) compared to healthy tissue." (PMID 32781555, 2020). "Recently, circ-PPP1R12A was screened for elevated expression in colon cancer cytoplasm." (PMID 35992800, 2022). "Similarly, a protein encoded by circ-PPP1R12A activates the Hippo/YAP pathway and promotes the migration, invasion, and proliferation of colon cancer cells." (PMID 34205978, 2021). "circ-PPP1R12A is another intriguing case, since not the circRNA itself but a protein encoded by that was shown to facilitate the migration, invasion, and proliferation of colon cancer cells." (PMID 34205978, 2021). "To investigate the correlation between PPP1R12A and RFS in subgroups of patients, we performed RFS analysis among IIIB, IIIC, colon cancer, and rectal cancer, respectively." (PMID 26113782, 2015). "The protein’s influence on colon cancer cells is correlated with PPP1R12A-73aa up-regulation but not with the over-expression of its circRNA." (PMID 32781555, 2020).
ovarian carcinoma (6 papers, 2020 to 2025). A malignant neoplasm originating from the surface ovarian epithelium. "Incubation of ovarian cancer cell lines with platelets induced the association of PPP1R12A with YAP, coincidentally with YAP dephosphorylation and cellular resistance to anoikis, a type of apoptosis induced by loss of cell adhesion or inappropriate cell adhesion." (PMID 37957190, 2023). "PPP1R12A expression is downregulated in ovarian cancer tissues, and this promotes cell proliferation." (PMID 34180758, 2021).
lung carcinoma (4 papers, 2017 to 2025). "Besides, it was reported that a significantly higher cytoplasmic and membranous PPP1R12A expression was found in pancreatic compared to biliary, colon breast and lung cancers, suggesting the specificity of PPP1R12A to pancreatic cancer over other solid cancers." (PMID 36737824, 2023).
breast carcinoma (3 papers, 2023 to 2025). "Cohort data available from the Cancer Genome Atlas showed that high expression of PPP1R12A, PP1B encoding the catalytic subunit of the myosin phosphatase complex, or ATP8A1 correlated with poor prognosis in breast cancer patients." (PMID 37957190, 2023). "Combined with the present results using MDA-MB-231 cells, the active “ATP8A1-PS-YAP phosphatase (PPP1R12A/PP1B)” axis may account for the poor prognosis of breast cancer patients through YAP activation." (PMID 37957190, 2023). "Kaplan–Meier survival curves from TCGA cohort data indicated that high expression of ATP8A1, PPP1R12A, or PP1B correlated with shorter overall survival periods for breast cancer patients." (PMID 37957190, 2023). "Cohort data available from TCGA showed that high expression of PPP1R12A, PP1B, or ATP8A1 correlated with poor prognosis in breast cancer patients." (PMID 37957190, 2023). "Therefore, we sought to ask whether ATP8A1, PPP1R12A, or PP1B, which we suggested as YAP-activating factors in the previous and the present study, was related to the prognosis of breast cancer patients." (PMID 37957190, 2023).
holoprosencephaly (3 papers, 2021 to 2024). Holoprosencephaly (HPE) is a complex brain malformation resulting from incomplete cleavage of the prosencephalon, occurring between the 18th and 28th day of gestation, and affecting both the forebrain and face, which results in neurological manifestations and facial anomalies of variable severity. "In the case of PPP1R12A, its loss-of-function causes holoprosencephaly and ID in individuals with stop gain variants and deletions/duplications, resulting in a frameshift effect." (PMID 33922640, 2021). "KIF14 (OMIM ID: 611279) and CEP55 (OMIM ID: 610000), like CIT, are recessively inherited etiologies of microcephaly, whereas variants in PPP1R12A (OMIM ID: 602021) are responsible for a de novo dominant form of a holoprosencephaly spectrum that includes individuals with microcephaly." (PMID 39316437, 2024).
pancreatic cancer (3 papers, 2021 to 2023). "In the context of pancreatic cancer, it has been shown that the expression of PPP1R12A was significantly higher in the tumour tissues compared with the normal tissues at both the mRNA and protein levels." (PMID 36737824, 2023). "On top of that, the expression of PPP1R12A was also detected in cancer that was invading pancreatic nerves and regional lymph nodes, indicating that PPP1R12A may play a role in the metastasis of pancreatic cancer." (PMID 36737824, 2023).
colorectal cancer (2 papers, 2015 to 2021). A primary or metastatic malignant neoplasm that affects the colon or rectum. "Thus, we hypothesize that PPP1R12A associates with the recurrence and overall survival in colorectal cancer." (PMID 26113782, 2015). "Here for the first time we conducted the study to examine the possibility of PPP1R12A as a possible biomarker for the prediction of clinical outcomes in stage III colorectal cancer patients treated with oxaliplatin-based chemotherapy." (PMID 26113782, 2015). "The copy number of PPP1R12A has also been reported as an independent predictor of overall survival and recurrence in stage III colorectal cancer patients." (PMID 34180758, 2021). "In conclusion, our study demonstrates that the copy number of PPP1R12A could independently predict recurrence and overall survival of stage III colorectal cancer patients receiving oxaliplatin-based adjuvant chemotherapy." (PMID 26113782, 2015). "However, so far there have been no studies exploring the correlation between PPP1R12A and clinical outcomes in colorectal cancer." (PMID 26113782, 2015).
ovarian tumor (2 papers, 2020 to 2021). "We show that MYPT1 (PPP1R12A), encoding myosin phosphatase target subunit 1, is downregulated in ovarian tumors, leading to reduced survival and increased tumorigenesis, as well as resistance to platinum-based therapy." (PMID 31926547, 2020).
serous ovarian cancer (2 papers, 2021 to 2024). "The expression profiles of SDF2L1, PPP1R12A, and PRKG1 were associated with the clinical outcomes of high-grade serous ovarian cancer." (PMID 34745201, 2021).
ductal carcinoma (1 paper, 2011). "Mcs6 human orthologous transcripts that have been reported as differentially expressed between non-diseased breast tissue and ductal carcinoma tissue encode for two phosphatases (DUSP6, PPP1R12A), a proteoglycan (EPYC), a redox regulator (TXNRD1), and two uncharacterized proteins (ALX1, ZDHHC17)." (PMID 21625632, 2011).
glioblastoma (1 paper, 2022). The most malignant astrocytic tumor (WHO grade IV). "Finally, the present study allowed us to identify prognostic proteins for glioblastoma: PPP1R12A and RPS14 are favorable prognostic markers while ALCAM, ANXA11, and AltProt IP_652563 are unfavorable prognostic markers." (PMID 36333286, 2022).
jejunal atresia (1 paper, 2026). "This case broadens the phenotypic spectrum associated with PPP1R12A mutations by highlighting isolated growth hormone deficiency and jejunal atresia in the absence of genitourinary and neurodevelopmental anomalies." (PMID 41626296, 2026).
liver cirrhosis (1 paper, 2023). "Obviously, the expressions of PPP1R12A, SP1 and SMARCAD1 in HCC tissues were higher than those in the liver cirrhosis tissues, which were opposite to the expression trend of KLF2 in HCC." (PMID 37386390, 2023).
lymph node metastasis (1 paper, 2015). "After adjusting for age, location, gender, TNM, lymph node metastasis, and histology grade, PPP1R12A remained an independent factor associated with RFS." (PMID 26113782, 2015). "High lymph node metastasis (lymph node ≥ 4: HR = 2.160, P = 0.007), high TNM stage (IIIC: HR = 4.001, P < 0.001), and low RCN of PPP1R12A (RCN < 0.37: HR = 2.186, P = 0.003) were significantly associated with poor RFS." (PMID 26113782, 2015). "Poor differentiation (HR = 2.310, P = 0.011), high lymph node metastasis (lymph node ≥ 4: HR = 2.750, P = 0.001), high TNM stage (IIIC: HR = 3.613, P < 0.001), and low PPP1R12A RCN (RCN < 0.37: HR = 2.782, P < 0.001) were shown to be significantly associated with poor OS." (PMID 26113782, 2015).
osteosarcoma (1 paper, 2022). A usually aggressive malignant bone-forming mesenchymal neoplasm, predominantly affecting adolescents and young adults. "Together, the results suggest that in osteosarcoma cells under DNA damage, SETD7 is needed for cell cycle arrest through methylation of pRb or E2F-1 or PPP1R12A." (PMID 35326563, 2022).
sex development disorders (1 paper, 2022). "PPP1R12A loss-of-function heterozygous pathogenic variants have been associated with a congenital malformation syndrome affecting the embryogenesis of genitourinary and brain systems (GUBS; OMIM *618820) including sex development disorders." (PMID 35627165, 2022). "No sex development disorders have been recorded for 12q21 deletions involving PPP1R12A, but brain and genitourinary defects are recurrent." (PMID 35627165, 2022).
triple-negative breast carcinoma (1 paper, 2023). An invasive breast carcinoma which is negative for expression of estrogen receptor (ER), progesterone receptor (PR), and human epidermal growth factor receptor 2 (HER2). "Knockdown experiments of these phosphatases suggested that PPP1R12A, a regulatory subunit of the myosin phosphatase complex, was essential for YAP-dependent proliferation of triple-negative breast cancer MDA-MB-231 cells." (PMID 37957190, 2023).
urogenital and brain malformation syndrome (1 paper, 2026). "Notably, he lacks genitourinary anomalies, which are frequently described in individuals with PPP1R12A-related urogenital and brain malformation syndrome (UBMS)." (PMID 41626296, 2026).
tumor (37 papers, 2010 to 2025). "Taken together, these data indicate that miR-455-5p play a critical role in controlling CCA growth and mediating the anti-tumor effects of galangin, at least in part, through targeting PPP1R12A and modulating MAPK and PI3K/AKT pathway." (PMID 34149934, 2021). "Merlin, a tumor suppressor, is activated when the serine 518 is dephosphorylated by the PPP1R12A–PP1cδ." (PMID 26113782, 2015). "Additionally, we found other abundant proteins in PDAC samples implicated in cytoskeletal dynamics, cell motility and tumor progression such as TUBB4A, SEPTIN7, ARHGDIA, THBS1, and PPP1R12A, similar to reports from the literature." (PMID 41007761, 2025). "We previously identified that PPP1R12A could inhibit angiogenesis and tumor growth, and has been identified as a promising prognostic factor for human PCa." (PMID 34484299, 2021). "However, we corroborated the tumor-suppressive roles of insertions in Adk and Zbtb20 and in Nipbl, Pdlim5, Ppp1r12a, Tnrc6b, Brd4, Cul3, Ctnna3, Elavl1, Gphn, Nfia, Ptpn12, Taok3, and Rasa1." (PMID 33435458, 2021). "Collectively, these data indicate that miR-455-5p affects CCA cells survival and metastasis and mediates galangin's anti-tumor effects may through modulating PPP1R12A expression and MAPK and PI3K/AKT pathway." (PMID 34149934, 2021). "This is an intergenic SNP that lies between PAWR and PPP1R12A and it may be in linkage disequilibrium with functional variants in either gene, although PAWR as a tumor suppressor is a more likely candidate." (PMID 21358824, 2011). "Importantly, PPP1R12A could inhibit angiogenesis and tumor growth and predict aggressive outcomes in PCa." (PMID 34484299, 2021). "In contrast, circ-HIPK3 and circ-PPP1R12A are significantly upregulated in CRC and function as oncogenes through the promotion of tumor cell proliferation and metastasis." (PMID 34660182, 2021). "Taken together, it is conceivable that the EV PPP1R12A may reflect the effect of PDAC cells whereas SCN7A and SGCD may represent essential components from the tumour microenvironment, i.e., immune cells, fibroblasts and Schwann cells." (PMID 36737824, 2023). "In summary, these data demonstrated that inhibition of PPP1R12A expression suppresses CCA cells survival and metastasis and may mediate the anti-tumor effects of miR-455-5p." (PMID 34149934, 2021). "In summary, our findings demonstrate that miR-455-5p mediates galangin's anti-tumor effect and inhibits CCA cells proliferation, migration, and invasion, at least in part, by targeting PPP1R12A, an effect that decreases MAPK and PI3K/Akt pathway activation in CCA cells." (PMID 34149934, 2021). "PPP1R12A, the substrate specifying subunit for MLCP, was identified as being down-regulated in PC vs matched normal prostate, but more specifically, down-regulated at sites of metastasis vs primary tumours and matched normal prostate." (PMID 29423094, 2018). "GGCT expression was significantly upregulated in tumor tissues, while AOX1, NT5E, PPP1R12A, and PTGS2 were significantly downregulated compared to normal tissues in the TCGA cohort." (PMID 34484299, 2021).
cancer (30 papers, 2013 to 2025). A tumor composed of atypical neoplastic, often pleomorphic cells that invade other tissues. "Two potential targets enriched in ‘proteoglycans in cancer’ pathway, PPP1R12A and PPP1R12B, were downregulated at both the mRNA and protein levels." (PMID 34180758, 2021). "On the other hand, PPP1R12A, also called the myosin-binding subunit of myosin phosphatase, is one of the subunits of myosin phosphatase, which is frequently expressed at a low level in human cancers." (PMID 30925892, 2019). "Comparison of primary vulval squamous cell carcinoma (VSCC) cells and vulval carcinoma-associated fibroblasts (VCAF) isolated from the same patient confirmed that depletion of PPP1R12A had a stronger effect in cancer cells." (PMID 28737169, 2017). "In particular, APE1 promotes YBX1 dual-phosphorylation at S174 and S176 by modulating PPP1R12A and PLK1 to enhance SG formation and cancer cell survival." (PMID 38436697, 2024). "We then focused on two target genes, PPP1R12A and PPP1R12B, for subsequent analysis, as both are members of the same gene family and enriched in the pathway of focal adhesion, proteoglycans in cancer and regulation of the actin cytoskeleton." (PMID 34180758, 2021). "Enhancing actomyosin contractility through PPP1R12A or PPP1CB depletion led to nuclear rupture in HeLa, MDA-MB-231, A549, SiHa and HT1080 cancer cells but had little effect on nuclear integrity in telomerase-immortalized hTERT RPE-1 cells and BJ-5ta primary fibroblasts." (PMID 28737169, 2017).
neurodevelopmental disorder (1 paper, 2023). A behavioral and cognitive disorder with onset during the developmental period that involves impaired or aberrant development of intellectual, motor, or social functions. "One of the identified GUS, PPP1R12A, successively has been confirmed as disease‐gene of Genitourinary and/orbrain malformation syndrome (OMIM #618820), while a recent publication correlates SYNCRIP mutations in a new neurodevelopmental disorder." (PMID 38041506, 2023). "Of the 15 GUSs encountered, two have recently become disease genes: particularly, PPP1R12A gene has been associated with Genitourinary and/or brain malformation syndrome (OMIM #618820), while SYNCRIP gene is implicated in a new neurodevelopmental disorder." (PMID 38041506, 2023).
PPP1R12A also shares sentences with these, for which no sentence is quoted: Hypertension (8 papers); prostate carcinoma (7); infection (6); diabetes (5); asthma (3); glioma (3); heart failure (3); hepatocellular carcinoma (3); atherosclerosis (2); atrial fibrillation (2); endothelial dysfunction (2); erectile dysfunction (2); essential hypertension (2); gastric cancer (2); Hyperglycemia (2); neuroblastoma (2); non-small cell lung carcinoma (2); pulmonary fibrosis (2); Sepsis (2); adenovirus infection (1); allergic asthma (1); Arrhythmia (1); bladder cancer (1); cardiomyopathy (1); colitis (1); congenital malformation syndrome (1); diabetic nephropathy (1); end-stage renal disease (1); energy metabolism disorder (1); fibrosarcoma (1).
A further 28 diseases each share a sentence with PPP1R12A in 1 paper.